APOL1 (apolipoprotein L1)
Diseases named in the same sentence as APOL1 in open-access papers (continued):
Sharing a sentence is not in itself a finding about the gene and the disease.
Nephropathy (continued). "They found that the presence of JCV viruria in patients with increased risk of APOL1-associated nephropathy was negatively associated with albuminuria and CKD (eGFR <60 mL/min/1.73 m2)." (PMID 35138324, 2022). "Urinary tract JCV infection was measured in African Americans in order to access relationships with apolipoprotein L1 gene (APOL1)–associated nephropathy." (PMID 34457361, 2021). "The association between high-risk APOL1 genotypes and kidney damage is highly important for understanding the ethnic differences in the onset of AKI in patients with COVID-19." (PMID 35145920, 2021). "In human APOL1 nephropathy, APOL1 variant risk status appears to be insufficient for disease onset and a second factor, generally increased APOL1 expression, appears to be required." (PMID 34765626, 2021). "Such as viral infection, the link between viremia and APOL1 nephropathy also supports the idea that the virus can activate the APOL1 response to cause kidney damage." (PMID 35145920, 2021). "There was a single study with individuals from West Africa, highlighting the lack of ‘omics research in continental Africans, despite many studies documenting the well-established genetic link to CKD in African Americans (APOL1-associated nephropathy)." (PMID 34819944, 2021). "APOL1-nephropathy, driven by relatively common and penetrant variants, provides an opportunity to understand and more effectively treat a significant subset of patients with kidney disease." (PMID 34350953, 2021). "Although APOL1-nephropathy risk primarily fits a recessive model, there is a small increased risk of FSGS, HIVAN and H-ESKD in G1 heterozygotes." (PMID 34350953, 2021). "Individuals with high-risk genotypes are more likely to develop albuminuria, and many APOL1-associated nephropathies (e.g. HIVAN and FSGS) often present with nephrotic range proteinuria." (PMID 34350953, 2021). "Cell death: Enhanced cell death rate has been reported among various pathways leading to kidney damage associated with APOL1 RVs." (PMID 34440683, 2021). "Surprisingly, JCV urinary shedding was associated with lower rates of nephropathy in individuals with APOL1 high-risk genotypes." (PMID 34457361, 2021). "A polymorphism in the gene encoding apolipoprotein L1 (APOL1) has been associated with the development of several nephropathies, including hypertension-attributed nephropathy, and glomerulopathies like HIV-associated nephropathy (HIVAN) and idiopathic FSGS." (PMID 33348903, 2020). "Retrospective transplantation studies have shown that APOL1 associated risk for nephropathy is conferred by the genotype of donor tissue, suggesting that nephropathy is likely induced by locally translated APOL1 within populations of kidney cells." (PMID 31158233, 2019). "Because of an incomplete penetrance of the APOL1 risk alleles, environmental factors have been proposed as the key triggers of APOL1 expression and kidney damage in African Americans18." (PMID 31664093, 2019). "Recent studies have demonstrated a strong association between ESRD in African Americans with LN and APOL1 nephropathy risk alleles G1 and G27; however, the mechanism underlying this association remains elusive." (PMID 31664093, 2019). "Targeting APOL1, PKR or other components of pathways downstream of activated PKR opens novel therapeutic approaches to treating APOL1-associated nephropathy." (PMID 30417125, 2018). "Previous reports provided strong statistical evidence implicating APOL1 as the major contributor to nephropathy risk in African Americans, driven by two coding variants, termed G1 and G2." (PMID 26147622, 2015). "For all 675 kidneys transplanted from donors at both centers, kidneys from AA deceased donors with two APOL1 nephropathy variants reproducibly associate with higher risk for allograft failure after transplantation (HR 2.26; p = 0.001)." (PMID 26156092, 2015).
Nephropathy (continued). "Among African Americans and West Africans, the role of the nephropathy-associated APOL1 variant, rs73885319, was also assessed." (PMID 22973513, 2012). "A known nephropathy-associated variant (rs73885319) in the APOL1 gene, which encodes an HDL-associated apolipoprotein, was investigated among AA." (PMID 22973513, 2012). "Since HIV infection increases the risk for nephropathy by a factor of nearly fivefold, it is possible that other environmental or genetic factors interact with APOL1 and/or MYH9 to mediate risk of renal disease." (PMID 21698141, 2011). "Herein, we scanned the genome to detect polymorphisms mediating risk for T2DM-ESRD, conditional on APOL1 G1/G2 nephropathy risk variants and the MYH9 E1 risk haplotype using case-control and case-only study designs." (PMID 21698141, 2011). "The observed interactions between suPAR and ApoL1 variants provide a molecular framework for understanding how genetic risk factors for kidney disease interact with innate immune activation to accelerate nephropathy." (PMID 41480757, 2026). "In African American patients, APOL1-associated nephropathy may be misdiagnosed as HN when it is a primary glomerular disease." (PMID 41141162, 2025). "Thus, investigating FSGS from a genetic standpoint, with a specific focus on APOL1 and its associated nephropathies, has become pivotal for elucidating the disease’s pathogenesis." (PMID 40948471, 2025). "The term "hypertensive nephrosclerosis" itself encompasses heterogeneous pathogenic processes and may mask the underlying primary renal diseases (for example, APOL1 gene-associated nephropathy) that coincide with hypertension." (PMID 41141162, 2025). "APOL1-associated kidney damage primarily affects podocytes, accelerating glomerulosclerosis." (PMID 40213244, 2025). "Beyond highlighting UM30-OSN cells as a viable alternative to commonly used cell lines of Caucasian origin such as HEK-293 and the immortalized podocyte cells, our study also supports their application as a disease-relevant in vitro model for investigating APOL1-associated nephropathies." (PMID 41225540, 2025). "Classification systems may evolve, with “hypertensive nephrosclerosis” replaced by more precise terms like “APOL1-associated nephropathy” or “arterionephrosclerosis of aging”." (PMID 41141162, 2025). "Moreover, since IFN-I–induced APOL1 variant nephropathy is linked to both podocyte ER stress and fibrosis, it is possible that in the kidney, the APOL1 variants G1 and G2 mimic APOL2 activity in the liver." (PMID 40503184, 2025). "Specifically, variants in the apolipoprotein L1 (APOL1) gene have been linked to APOL1 nephropathy." (PMID 38765814, 2024). ",4, 5, 6 These associations are strongest in severe forms of nephropathy, and weaker with mild disease, indicating that APOL1 might contribute to more rapid disease progression." (PMID 38360481, 2024). "As podocytes are hypothesized to be highly vulnerable in APOL1-associated nephropathy, we investigated kidney organoid podocytes for evidence of injury associated with IFN-γ treatment." (PMID 38838223, 2024). "We found that a protective pool of select SNARE (N-ethylmaleimide sensitive factor attachment protein receptors) proteins (Syx7, Ykt6 and, Syb) play a critical role in this process, uncovering new potential therapeutic targets to prevent the progression of APOL1-associated nephropathies." (PMID 37925499, 2023). "Divers at al.12 tested whether infection by JCV and BKV modulated the association between APOL1 and development of nephropathy." (PMID 35138324, 2022). "In addition, we found a significant association of rs136161 located in the Apolipoprotein L1 coding gene (APOL1) with T2DM nephropathy, which has been already linked to an advanced diabetic kidney disease across multiple ethnic groups." (PMID 33430853, 2021). "Divers at al. tested whether infection by JCV and BKV modulated the association between APOL1 and the development of nephropathy." (PMID 34457361, 2021).
Nephropathy (continued). "APOL1-nephropathy risk follows a recessive mode of inheritance." (PMID 34350953, 2021). "Thus, APOL1 renal risk variant-enhanced inflammatory processes are involved in the pathogenesis of nephropathy." (PMID 32854642, 2020). "Thus, identification of factors that upregulate APOL1 expression in lupus is critical for designing new therapies aimed to prevent or reduce the severity of kidney damage in individuals expressing the APOL1 risk alleles." (PMID 31664093, 2019). "Pore formation has also been reported to occur in HEK293 cells when APOL1 is over-expressed, bolstering an emerging hypothesis that APOL1-associated kidney damage may be due to toxic APOL1-mediated pore formation." (PMID 31158233, 2019). "There are two nephropathy-associated variants of APOL1, referred to as APOL1 G1 and G2." (PMID 31158233, 2019). "However, the occurrence of HIV associated nephropathy is less likely in the present study because Ethiopians have low prevalence of APOL1 risk variants." (PMID 30863641, 2019). "However, the underlying molecular mechanisms for APOL1-associated nephropathy are still poorly understood." (PMID 29967295, 2018). "Although the nephropathy association with MYH9 is markedly attenuated after accounting for the coding variants in APOL1, three groups observe independent MYH9 association with non-diabetic nephropathy (personal communication 2010: Jeffrey Kopp; Carl Langefeld; Linda Kao)." (PMID 21698141, 2011). "In addition to the nephropathy risk imparted by APOL1 G1 and G2 variants, our results support residual nephropathy risk residing within MYH9, or other c22 variants in linkage disequilibrium with the MYH9 E1 haplotype." (PMID 21698141, 2011). "Moreover, I provide evidence that the site of DP interaction with APOL2 precisely coincides with an APOL1 cholesterol-binding motif involved in kidney podocyte cytotoxicity causing APOL1 variant nephropathy, linking APOL-induced pathologies of these 2 diseases." (PMID 40503184, 2025). "This discrepancy suggests that APOL1-mediated cytotoxicity, believed to manifest only beyond a certain expression threshold, might require additional modifying factors to induce APOL1-associated nephropathy." (PMID 38542298, 2024). "In two CKD cohorts, APOL1 risk genotypes were found in 29% of African ancestry patients and in 7% of Hispanic patients, and they were frequently found in patients with a diagnosis of nephropathy of unknown origin (24%)." (PMID 35207681, 2022). "Finally, we provide functional evidence in vivo that the G2-altered APOL1 may be interacting with MYH9 to confer nephropathy risk." (PMID 26147622, 2015). "Despite the protective role of APOL1 variants in the context of infectious disease, these variants are deleterious in a chronic disease context: through unknown mechanisms, variants increase the risk of nephropathy in African Americans." (PMID 22973513, 2012). "It includes well-established acronyms like FSGS and encompasses subtypes such as APOL1-associated and HIV-associated nephropathy." (PMID 39925878, 2025). "This study reports a novel APOL1 mutation (p.T272I) identified in a pair of Chinese twins with FSGS, expanding the genetic spectrum of APOL1-related nephropathies." (PMID 40948471, 2025). "Numerous reports confirm that APOL1 risk alleles increase the risk for focal segmental glomerulosclerosis, HIV-associated nephropathy, and COVID-19-associated nephropathy, all of which fall within the spectrum of APOL1-mediated kidney disease (AMKD)." (PMID 40501951, 2025). "Together, these results highlight the interplay between APOL1 RRVs, hypoxia, inflammation, fibrosis, and tubular injury, all of which are key drivers of the heterogeneity and severity seen in APOL1-mediated nephropathy." (PMID 41010023, 2025). "As NCOR2 is involved in both renal lipid metabolism and inflammation, it is possible that regulation of this gene presents a novel pathway to development of APOL1 nephropathy in those with HIV." (PMID 39448372, 2025).
Nephropathy (continued). "The epigenetic age of our participants with APOL1 nephropathy who generally had well controlled HIV is in keeping with these findings." (PMID 39448372, 2025). "The phenotype of APOL3 KO or APOL1Δ podocytes provides a clear confirmation that APOL1 nephropathy can occur independently from APOL1 cation pore-forming activity." (PMID 39451256, 2024). "People of African descent are known to carry APOL1 kidney disease risk variants, which are strongly associated with the progression of HIV-associated nephropathy to CKD and ESRD during HIV infection." (PMID 39056083, 2024). "Kidney diseases that are known to be associated with APOL1-driven pathology, including HIV-associated nephropathy, focal segmental glomerulosclerosis, and lupus nephritis, have been modeled in transgenic mice that express human APOL1 by several approaches." (PMID 36279295, 2022). "One of the major questions regarding APOL1 nephropathy is the mechanism whereby APOL1 RV elicit their toxicity in cells." (PMID 35159001, 2022). "APOL1-nephropathy has incomplete penetrance, with an estimated 15% lifetime risk for those with a high-risk genotype developing end-stage kidney disease (ESKD), suggesting there are non-genetic factors that modify risk." (PMID 34350953, 2021). "Inheriting two copies of these APOL1 risk variants, known as G1 and G2, causes high rates of focal segmental glomerulosclerosis (FSGS), HIV-associated nephropathy and hypertension-associated end-stage kidney disease." (PMID 34350953, 2021). "Together, these findings shed light on the recessive nature of APOL1-nephropathy and present an important model for future studies." (PMID 34350953, 2021). "Thus, the mechanisms underlying APOL1-nephropathy remain unclear." (PMID 34350953, 2021). "Together, these results show that transgenic expression of the human APOL1 gene under control of its endogenous promotor can recapitulate important features of APOL1-nephropathy seen in humans." (PMID 34350953, 2021). "In this study, we describe a mouse model of APOL1-nephropathy that not only resembles human disease in its response to a known disease trigger but also addresses questions regarding mode of inheritance and toxicity." (PMID 34350953, 2021). "Within the kidney, pCpG-Muγ treatment induced expression of APOL1 mRNA and APOL1 protein synthesis primarily in podocytes, supporting the idea that podocytes are crucial in at least some APOL1-nephropathies." (PMID 34350953, 2021). "The similarities between APOL1-nephropathy in this mouse model and humans present an opportunity to both understand disease mechanisms and to test potential APOL1-targeted therapies." (PMID 34350953, 2021). "To provide further insight into the genetics of APOL1-nephropathy, we developed a set of congenic bacterial artificial chromosome (BAC) transgenic mouse models." (PMID 34350953, 2021). "APOL1-induced nephropathy likely results from dose-dependent gain of cytotoxic function, which requires dosing of transcripts from two copies of the APOL1 G1/G2 alleles, combined with interferon-induced upregulation of their transcripts in podocytes." (PMID 34331942, 2021). "Approximately 87% of PLWHIV with CKD in Nigeria had 2 APOL1 risk alleles, and previous studies have showed that APOL1 genetic variants are strongly associated with HIV-associated nephropathy, a rapidly progressing kidney disease with severe tubular damage." (PMID 33066744, 2020). "Polymorphisms in the APOL1 gene account for the majority of excess risk of HIVAN attributed to African ancestry and of all APOL1-associated nephropathies, HIVAN has the strongest association with APOL1 risk genotypes." (PMID 29930940, 2018). "APOL1 risk variants are associated with 17-fold higher odds for FSGS and 29-fold higher odds for HIV-associated nephropathy." (PMID 27314022, 2016).
Nephropathy (continued). "We observed a significant decrease in myh9 expression when zebrafish embryos were injected with the proposed dominant-negative APOL1 G2 allele alone (21% reduction; p = 0.043), suggesting that the mutant protein may be suppressing myh9, either directly or indirectly, to induce nephropathy." (PMID 26147622, 2015). "Further studies are needed to elucidate the functional impacts of the altered APOL1 protein to nephropathy." (PMID 26147622, 2015). "To further explore the findings in African ancestry populations, we investigated the role of an African ancestry-specific nephropathy risk variant, rs73885319, in the gene encoding HDL-associated APOL1." (PMID 22973513, 2012). "The strong association observed between variants in APOL1 and near the MYH9 gene with several kidney diseases was a major breakthrough in our understanding of nephropathy susceptibility in AA." (PMID 21698141, 2011). "In our study, the SCARB1 signal (cg14849578) was found to be hypermethylated in those with kidney disease including APOL1 nephropathy, and results from the BIOS-BBMRI dataset show that this methylation signal was negatively associated with SCARB1 gene expression." (PMID 39448372, 2025). "Further investigation of pathways linking DNA methylation to APOL1 nephropathies is warranted." (PMID 39448372, 2025). "Elevated interferon (IFN) signaling is associated with kidney diseases including COVID-19, HIV, and apolipoprotein-L1 (APOL1) nephropathy, but whether IFNs directly contribute to nephrotoxicity remains unclear." (PMID 38838223, 2024). "We hypothesized that PKR activation is a mechanistic pathway shared by HIV- and APOL1-mediated nephropathies, considering the high odds ratio for HIVAN among African Americans (OR 29) and South Africans (OR 89) carrying two APOL1 risk alleles." (PMID 39207915, 2024). "A previous study on the interactions between APOL1 and APOL3 suggested that deletion of APOL3 triggers intracellular actomyosin reorganization, increasing susceptibility to kidney disease through APOL1-induced podocyte dysfunction and kidney damage." (PMID 39163132, 2024). "An observation that might account for the multiple mechanisms that have been proposed for driving APOL1-related kidney damage." (PMID 38360481, 2024). "It would be interesting to test whether increasing the SNARE protein pool and treatment with inaxaplin complement each other in treating APOL1 nephropathy, as both act by binding APOL1 protein and, we suspect, act through different pathways." (PMID 37925499, 2023). "Therefore, all our transgenic constructs are physiologically relevant and carry common natural haplotypes seen in people of African ancestry who develop APOL1 nephropathies." (PMID 37925499, 2023). "A distinctive feature of COVID-19–associated nephropathy (COVAN; also known as COVID-19–associated collapsing glomerulopathy) is its near-exclusive predilection for Black people who carry 2 risk alleles of apolipoprotein L1 (APOL1)." (PMID 35472001, 2022). "Some but not all African-Americans (AA) who carry APOL1 nephropathy risk variants (APOL1) develop kidney failure (end-stage kidney disease, ESKD)." (PMID 36250097, 2022). "Overall, the results from these modified transgenic lines suggest that the recessive nature of APOL1-nephropathy risk in this model is not easily explained by the G0-mediated rescue of risk variant toxicity." (PMID 34350953, 2021). "In addition to modeling important features of human APOL1-nephropathy, this coisogenic APOL1 model provides an opportunity to examine genotype differences." (PMID 34350953, 2021). "Further, mice with a multicopy G2 transgene (G2multi/G2multi) showed the greatest proteinuria response with worst prognosis, supporting the recessive nature of APOL1-nephropathy and the notion that disease is a function of the expression level of APOL1 risk variant." (PMID 34765626, 2021).